ATOH7 (atonal bHLH transcription factor 7)
Description:
Transcription factor that binds to DNA at the consensus sequence 5'-CAG[GC]TG-3'. Dimerization with TCF3 isoform E47 may be required in certain situations. Binds to gene promoters and enhancer elements, and thereby regulates a transcriptional program of retinal ganglion cell (RGC) determinant genes (By similarity). Although the exact mechanism is not certain, retinal transcription regulation by ATOH7 has a role in RGC determination and survival, photoreceptor population development, targeting of RGC axons to the optic nerve and development of the retino-hypothalamic tract (By similarity). Binds to its own promoter and enhancer sequences, suggesting autoregulation of ATOH7 transcription (By similarity). Required for retinal circadian rhythm photoentrainment (By similarity). Plays a role in brainstem auditory signaling and binaural processing (By similarity).
Synonyms: bHLHa13; Math5; NCRNA; PHPVAR; RNANC
Tractability: No criterion of Open Targets' tractability assessment is met for any kind of drug.
Gene: Protein-coding gene on chromosome 10 (68,230,595 to 68,232,113, reverse strand). Ensembl gene ENSG00000179774.
Subcellular location: Nucleus; Perikaryon; Cell projection, axon
Subcellular location (Human Protein Atlas): Flagellar centriole; Nucleoplasm; Cytosol; Mid piece
Gene Ontology:
Molecular function: protein binding; sequence-specific double-stranded DNA binding; transcription cis-regulatory region binding; DNA-binding transcription factor activity, RNA polymerase II-specific; E-box binding; protein dimerization activity
Biological process: neural retina development; optic nerve development; positive regulation of transcription by RNA polymerase II; axon development; entrainment of circadian clock by photoperiod; neuron fate commitment; positive regulation of retinal ganglion cell axon guidance; regulation of transcription by RNA polymerase II; response to auditory stimulus; sensory organ development; regulation of DNA-templated transcription; system development
Cellular component: nucleoplasm; nucleus; axon; chromatin; perikaryon
Genetic constraint (gnomAD): Loss-of-function variants: 10 observed, 9.13 expected, observed/expected ratio (o/e) 1.09, 90% interval 0.67 to 1.76. That is too few expected variants to judge how well the gene tolerates losing a copy. Missense variants: 230 observed, 184.66 expected, observed/expected ratio (o/e) 1.25, 90% interval 1.12 to 1.39. Synonymous variants: 97 observed, 83.66 expected, observed/expected ratio (o/e) 1.16, 90% interval 0.98 to 1.37.
Homologues: Orthologues: chimpanzee ATOH7 (100% identical), macaque ATOH7 (96% identical), pig ATOH7 (92% identical), dog ATOH7 (91% identical), rabbit ATOH7 (91% identical), mouse Atoh7 (83% identical), rat Atoh7 (80% identical), zebrafish atoh7 (48% identical), tropical clawed frog atoh7 (47% identical), Drosophila melanogaster ato (32% identical), Drosophila melanogaster amos (29% identical), Caenorhabditis elegans lin-32 (25% identical), and 2 more. Paralogues in human: ATOH1 (36% identical), NEUROD1 (30% identical), NEUROD2 (30% identical), NEUROD6 (29% identical), NEUROD4 (28% identical), NEUROG1 (28% identical), NEUROG2 (28% identical), BHLHA15 (27% identical), NEUROG3 (26% identical), OLIG2 (24% identical), BHLHE22 (23% identical), OLIG1 (23% identical), and 3 more.
Diseases named in the same sentence as ATOH7 in open-access papers:
ATOH7 is named in the same sentence as 24 diseases in open-access papers, as found by Europe PMC text mining. Sharing a sentence is not in itself a finding about the gene and the disease. The quoted sentences say what the papers report.
glaucoma (11 papers, 2012 to 2022). Increased pressure in the eyeball due to obstruction of the outflow of aqueous humor. "Variants in ATOH7 have also been associated with primary open angle glaucoma and endophenotypes of glaucoma such as optic disc size, indicating its key role in maintaining these structures." (PMID 34576164, 2021). "Mutations in ATOH7 or in its promoter result in a myriad of optic disorders including optic nerve hypoplasia, persistent hyperplasia of the primary vitreous and primary open angle glaucoma." (PMID 28662219, 2017). "In addition, a suggestive protective association was also noted for rs7916697 in Afro-Caribbean Barbados population in POAG indicating ATOH7 as an important susceptibility gene associated with glaucoma and optic disc parameters." (PMID 30519491, 2018). "Several polymorphisms in the genes SIX6 and ATOH7 were identified that are responsible for thinner retinal nerve fiber layer due to fewer RGCs, suggesting that humans with fewer RGCs are at increased risk of developing glaucoma." (PMID 29370175, 2018). "Studies in animal model of glaucoma have demonstrated that abnormal ATOH7 expression results in an increased number of differentiated RGCs." (PMID 30519491, 2018). "Furthermore, it has been reported that ATOH7 constitutes an important protein in the differentiation of Müller cells-derived retinal stem cells into RGCs in a rat model of glaucoma." (PMID 32545285, 2020). "Atoh7 promotes the differentiation of Müller cells-derived retinal stem cells into retinal ganglion cells by inhibiting Notch signaling, thus opening up a new avenue for gene therapy and optic nerve regeneration in glaucoma." (PMID 23945288, 2013). "A meta-analysis using data from six independent studies comprising 3,161 glaucoma cases and 42,837 controls found evidence for rs190004 (near ATOH7), rs1063192 (in CDKN2B and the overlapping gene CDKN2B-AS1) and rs10483727 (near SIX1 gene) significantly associated with POAG." (PMID 22761751, 2012). "GWAS have also reported a link between ATOH7 and raftlin lipid raft linker 1 (RFTN1) and glaucoma-related optic disc parameters." (PMID 32545285, 2020).
virus infection (3 papers, 2018 to 2021). "When ATOH7 virus was delivered to the subretinal space at stage 17, as normal retinogenesis was underway, viral infection caused a significant thickening of the RGC layer occupied by Brn3a-positive postmitotic RGCs by stage 35." (PMID 29717171, 2018). "ATOH7 virus infection carried out prior to the onset of neurogenesis at stage 10 resulted in increased Islet-1 and NF145 positive cells at stage 24 (Sup." (PMID 29717171, 2018). "Flow cytometry quantification further confirmed that ATOH7 virus infection resulted in a minor yet statistically significant increase of Visinin-positive cone photoreceptors from 13.5 ± 0.4% to 15.3 ± 0.5% (p < 0.05)." (PMID 29717171, 2018). "At stage 24, compared to control virus infected cells, ATOH7 virus infection increased NF68 and Islet-1 double positive cells from 14.4 ± 0.7% to 20.2 ± 0.9% (p < 0.01)." (PMID 29717171, 2018). "Compared with the control virus infection, ATOH7 virus infected progenitors showed a lower percentage of S phase cells (DNA contents > 2n but < 4n, p < 0.05) and a higher proportion of G2/M phase cells (DNA content = 4n, p < 0.05)." (PMID 29717171, 2018). "In addition, quantitative analyses showed that ATOH7 and Neurog2 virus infection altered cell cycle distributions among progenitors compared to controls." (PMID 34055784, 2021). "As shown on E9.5 retinal sections, control virus infected retinas and the regions lacking ATOH7 virus infection showed normal lamination and appeared healthy, whereas regions with augmented RGC genesis exhibited disrupted morphology and contained many pyknotic nuclei." (PMID 29717171, 2018).
Blindness (2 papers, 2015 to 2022). Blindness is the condition of lacking visual perception defined as a profound reduction in visual perception. "Nevertheless, as Atoh7 is solely expressed in the retina, no further developmental defects are described and lakritz mutant fish develop normally apart from their complete blindness." (PMID 26076409, 2015).
familial exudative vitreoretinopathies (2 papers, 2024). "A highly related condition that ATOH7 has also been associated with is familial exudative vitreoretinopathy (FEVR; OMIM: #133780, #601813, #616468), where the vascular changes are usually milder and the retinal detachment, instead, presents as incomplete and progressive." (PMID 38994994, 2024).
Anophthalmia (1 paper, 2020). Absence of the globe or eyeball. "Clinically, these forms of integrative multi-system analyses will undoubtedly influence our understanding of how early human RGC loss in conditions such as anophthalmia, primary congenital glaucoma and Atoh7 loss-of-function influence visual system development and behavior beyond conscious vision." (PMID 33288502, 2020).
neuroblastoma (1 paper, 2017). Neuroblastoma (NB) is the most common solid, extracranial childhood tumor. "In SH-SY5Y neuroblastoma cells, DcpS knockout or treatment with D157495 increased the mRNA levels of ATOH7 as well as the putative lncRNAs DRNT1 and DRNT2." (PMID 28662219, 2017).
retinal detachment (1 paper, 2021). An eye emergency condition which may lead to blindness if left untreated. "No variations were noted in genes known to cause Wagner syndrome or other retinal detachments (ATOH7, TSPAN12, LRP5, or NDP) or in genes known to cause ocular disease." (PMID 33776059, 2021).
retinoblastoma (1 paper, 2021). A malignant tumor that originates in the nuclear layer of the retina. "Thus, new spontaneous genetic events of ATOH7 may contribute potential normal differentiation function in retinoblastoma." (PMID 34815392, 2021).
infection (4 papers, 2018 to 2022). The state of being infected such as from the introduction of a foreign agent such as serum, vaccine, antigenic substance or organism. "Compared to the control RCAS virus infected retinas, which showed a well-defined neurogenic wave front demarcated by NF145, infection by RCAS.ATOH7 caused an expansion of the neurogenic area towards the peripheral retina." (PMID 29717171, 2018). "Both virally expressed ATOH7f and Neurog2 increased the number of endogenous ATOH7-expressing cells from 9.1 to 22.0% among total cells, and LV-NEP infection also increased the median ATOH7 expression level." (PMID 34055784, 2021). "Infection of the optic vesicle with the ATOH7 virus at HH stage 10 resulted in extensive transduction of the retina in both the preneurogenic and neurogenic regions at stage 18 as indicated by antiviral gag protein immunolabeling." (PMID 29717171, 2018). "Although infection of stage 17 chicken retina with ATOH7 virus led to the initial RGC overproduction, as the retina further developed, increased RGC death was detected." (PMID 29717171, 2018).
tumor (4 papers, 2014 to 2026). "Our findings suggest that the tumor initiation correlates with the timing and the cell type in which the “second hit” occurs: If the “second hit” happens before the emergence of ATOH7+ CPs, the tumorigenesis originates from the nascent CPs." (PMID 41535675, 2026).
degenerative diseases (1 paper, 2021). "Our study shows that elevating ATOH7 and Neurog2 expression in human retinal organoids significantly enhances early retinogenesis, which can serve as a useful approach to produce authentic human RGCs for studying development and degenerative diseases." (PMID 34055784, 2021).
ATOH7 also shares sentences with these, for which no sentence is quoted: Primary Open Angle Glaucoma (4 papers); optic nerve hypoplasia (2); coloboma (1); malaria (1); microphthalmia (1); myopia (1); nematode infections (1); optic atrophy (1); Optic neuropathy (1); primary congenital glaucoma (1); retinal diseases (1); Wagner syndrome (1); WAGR syndrome (1).